EZH2 (enhancer of zeste 2 polycomb repressive complex 2 subunit)
Diseases named in the same sentence as EZH2 in open-access papers (continued):
Sharing a sentence is not in itself a finding about the gene and the disease.
non-Hodgkin lymphoma (47 papers, 2013 to 2024). Distinct from Hodgkin lymphoma both morphologically and biologically, non-Hodgkin lymphoma (NHL) is characterized by the absence of Reed-Sternberg cells, can occur at any age, and usually presents as a localized or generalized lymphadenopathy associated with fever and weight loss. "For instance, TAZ-induced inhibition of EZH2 was shown to cause apoptotic activation in non-Hodgkin lymphoma cells." (PMID 38473991, 2024). "More recently, a selective small molecule inhibitor of EZH2 “Tazemetostat (EPZ-6438)” has been clinically tested in patients with relapsed or refractory solid tumors, non-Hodgkin’s lymphoma, or histiocytic disorders with EZH2 and other gene mutations." (PMID 36230787, 2022). "Hypertrimethylation can also be driven by the mutation of EZH2 alanine 687 to valine (A687V) in Non-Hodgkin’s lymphoma (NHL)." (PMID 33761979, 2021). "Heterozygous mutation on tyrosine 641 (Y641H, Y641S, Y641C, Y641F, and Y641N) is the most widely occurred EZH2 activating mutation in GC-originated non-Hodgkin lymphoma (NHL), accounting for approximately 22% of GC-DLBCL and FL." (PMID 31752930, 2019). "Recently, somatic mutations of EZH2 at Y641, and A677 were identified in 12–25 % non-Hodgkin lymphomas." (PMID 27316347, 2016). "Other studies have identified additional EZH2 gain-of-function point mutations at the alanine 677 and 687 residues in non-Hodgkin's lymphomas, which are associated with increased H3K27 trimethylation." (PMID 27793053, 2016). "Several groups have reported specific co-factor competitive EZH2 inhibitors, which have shown a strong capacity to reduce growth of cells expressing mutated forms of EZH2 (such as certain non-Hodgkin’s lymphoma)." (PMID 26300989, 2015). "Point mutations at Y641 of EZH2 are found in a subset of non-Hodgkin lymphoma patients; the enzymatic activity of both wild-type and mutant EZH2 are required for pathogenesis in these patients." (PMID 24157419, 2013). "Gain-of-function mutations and/or mutations in the catalytic SET domain of EZH2 have been identified in non-Hodgkin lymphoma (NHL), melanoma, and other cancers." (PMID 37461108, 2023). "EPZ-6438 demonstrated also robust in vivo activity in a EZH2-mutant non-Hodgkin lymphoma (NHL) mice xenograft model, causing dose-dependent tumor growth inhibition." (PMID 27222667, 2016). "Tazemetostat (TAZVERIK®), an epigenetic therapy for non-Hodgkin lymphoma (NHL), needed a diagnostic tool to identify mutations in the EZH2 gene." (PMID 38096164, 2023). "Tazemetostat (EPZ-6438) lead to potent antitumor activity in preclinical models of EZH2-mutant non-Hodgkin lymphoma (NHL)." (PMID 36671446, 2022). "A report showed anti-tumor efficacy for EPZ-6438, a selective inhibitor of EZH2, in Y646F-mutant xenograft tumors of non-Hodgkin lymphoma." (PMID 35795062, 2022). "EPZ-6438, also named tazemetostat, an inhibitor of EZH2, has entered phase II clinical trials for non-Hodgkin’s lymphoma treatment." (PMID 31065671, 2020). "Other gain-of-function hotspot mutations including Y641, A677, and A687 in the catalytic SET domain of EZH2 are prevalent, accounting for ~10–24% of non-Hodgkin's lymphoma." (PMID 30984620, 2019). "A phase 1 clinical trial of EZH2 inhibitor GSK2816126 in various non-Hodgkin lymphomas, solid tumors and MM was terminated due to insufficient evidence of clinical activity at the maximal dose and schedule attained (NCT02082977)." (PMID 30555699, 2018). "EZH2-mutant NHL (non-Hodgkin’s lymphoma) xenograft-bearing mice treated with EPZ-6438 had significant inhibition of tumour growth." (PMID 29757235, 2018). "EPZ6438, another orally available EZH2 inhibitor, decreases the levels of H3K27me3 in a dose-dependent manner leading to significant reduction of tumor growth in non-Hodgkin lymphoma expressing EZH2 mutant." (PMID 27793053, 2016). "Inhibition of EZH2 activity is proposed to inhibit tumor growth in non-Hodgkin's lymphoma via inducing the expression of BLIMP1 (a tumor suppressor)." (PMID 25605023, 2015).
non-Hodgkin lymphoma (continued). "In addition, EPZ-6438, another selective inhibitor of EZH2, exerted potent antitumor activity against EZH2-mutant non-Hodgkin's lymphoma." (PMID 30984620, 2019). "Recently, EZH2 inhibitors 16 and CPI-1205 (with an undisclosed structure) have entered clinical trials against EZH2 mutated non-Hodgkin lymphomas, while the results have not been disclosed." (PMID 27316347, 2016). "Activating mutations within the catalytic SET domain of EZH2, for example, are known in non-Hodgkin's lymphoma, but were absent in our tumor cohort." (PMID 26110843, 2015). "Treatment with EPZ-6438 dose-dependently decreased H3K27me3 levels and improved prognosis in EZH2-mutant non-Hodgkin lymphoma (NHL) mouse models." (PMID 28415635, 2017). "For example, three EZH2 inhibitors, tazemetostat (EPZ-6438), GSK2816126, and CPI-1205, have moved into phase I/phase II clinical trials in patients with non-Hodgkin lymphoma and genetically defined solid tumors." (PMID 36304988, 2022). "An oral inhibitor of EZH2, EPZ6438 (tazemetostat), reportedly decreases the levels of H3K27me3 to reduce tumor growth in EZH2 mutant non-Hodgkin lymphoma." (PMID 29556394, 2018). "EZH2 inhibitors EPZ-5687 from Epizyme® and GSK-2816126 from GlaxoSmithKline® for the treatment of non-Hodgkin's lymphoma are currently in clinical phases I/II and I, respectively." (PMID 26110843, 2015). "EZH2 inhibitors are currently in phase 2 clinical development in relapsed or refractory non-Hodgkin lymphoma (NHL) and biomarkers are needed for patient selection since neither EZH2 mutations nor H3K27me3 levels are sufficient to predict NHL cell response to EZH2 inhibitors." (PMID 30285865, 2018).
sarcoma (47 papers, 2012 to 2025). A usually aggressive malignant neoplasm of the soft tissue or bone. "This may represent a promising application of EZH2 inhibition to prevent tumor relapse as this may be caused by the drug-resistant and self-renewable sarcoma stem cells." (PMID 30683135, 2019). "EZH2 is also highly expressed in different sarcoma subtypes, and its silencing stops sarcoma cell proliferation." (PMID 40968252, 2025). "Whilst EZH2 favours oncogenic progression in PCa, LC and sarcomas, its function in breast malignancies seems to be quite different." (PMID 40968252, 2025). "A recent study identified the expression of Enhancer of Zeste homolog 2 (EZH2) in sarcoma CSCs that contributed to CSC resistance to doxorubicin chemotherapy." (PMID 40277903, 2025). "From five common sarcoma subtypes, we identified EZH2, a member of the PRC2 epigenetic complex, as being upregulated across the disease spectrum." (PMID 39789291, 2025). "Previous research indicated that EZH2 is significantly upregulated in various types of sarcoma, including Ewing sarcoma and synovial sarcoma, where its overexpression is associated with aggressive tumour behaviour and poor prognosis." (PMID 40464712, 2025). "Evaluating across sarcomas, this study has demonstrated the importance of EZH2 in sarcoma CSCs and established EZH2 as a potential therapeutic target." (PMID 39789291, 2025). "EZH2 inhibition in particular has been biologically and clinically viable, having shown efficacy in SMARCB1-deficient sarcomas." (PMID 39125735, 2024). "The FDA-approved drug Tazemetostat is a potent EZH2 inhibitor and was employed in these sarcoma patients." (PMID 39125735, 2024). "In recent years, EZH2 expression has also been discovered in certain sarcomas, including Ewing sarcoma, RMS, synovial sarcoma, osteosarcoma, and chondrosarcoma." (PMID 38146588, 2023). "Previous studies have reported the efficacy of immunotherapy and enhancer of the zeste homolog 2 (EZH2) inhibitor tazemetostat in various types of INI1-deficient tumors, such as sarcomas." (PMID 37667707, 2023). "Both sarcoma types showed similarly common high EZH2 expression (79% of the homologous elements, and 78.6% of the heterologous elements) and p16 expression (60% of the homologous elements and 72% of the heterologous elements)." (PMID 38146588, 2023). "As EZH2 inhibitor EPZ6438 (tazemetostat) recently received FDA approval for sarcoma treatment, we readily evaluated its potential to inhibit TNBC migration, invasion, and metastasis." (PMID 36446780, 2022). "Our analysis revealed that EZH2 is highly expressed in breast, bladder, head and neck, sarcoma, pancreatic, cervical, liver, and other cancers compared with in normal tissues." (PMID 35659256, 2022). "For instance, this experimental therapeutic approach, using the EZH2 inhibitor Tazemetostat in combination with Durvalumab, a PD-L1 inhibitor, is under investigation in clinical trials for solid tumors, including sarcomas (NCT04705818)." (PMID 34299136, 2021). "Another recent KMT inhibitor that targets EZH2 is tazemetostat, which is clinically used in sarcomas." (PMID 34540832, 2021). "Tazemetostat is a KMT inhibitor targeting EZH2 and G9a that has been approved for the treatment of sarcomas and sensitizes ovarian cells to DNA damage." (PMID 34540832, 2021). "We also performed a t-test analysis for each BIRC5, ERBB2 and EZH2 in TCGA sarcoma, uterine corpus endometrial carcinoma and ovarian serous cystadenocarcinoma." (PMID 29459674, 2018). "SDUS may be susceptible to EZH2 or CDK4/6 inhibition, and early evidence suggests that ERBB2/3-mutated S100/SOX10-positive sarcomas may benefit from HER2-targeted therapy." (PMID 41463261, 2025). "Targeting EZH2 with the selective inhibitor tazemetostat reduced sarcoma CSC survival, demonstrating that insights into the genetic signatures of CSCs may provide novel therapeutic opportunities to target these cells." (PMID 40277903, 2025).
sarcoma (continued). "The regulatory overlap of EZH2 with these pathways could give additional insights into sarcoma CSC biology." (PMID 39789291, 2025). "Taken together, these data support the hypothesis that EZH2 mediates the CSC phenotype in high-grade complex karyotype sarcomas and targeting of EZH2 sensitizes cells to anthracycline chemotherapy." (PMID 39789291, 2025). "In these conditions, EZH2 inhibition eradicates incurable sarcomas in vivo." (PMID 40968252, 2025). "However, the efficacy of EZH2 was subtle in clinical trials of its use in other sarcomas, especially when used as a single-agent therapy." (PMID 38310286, 2024). "Our previous results demonstrated that EZH2 might be a key modulator in bone development and sarcoma pathogenesis." (PMID 36622753, 2023). "In particular, EZH2 inhibitor is currently used in a phase 1 study in pediatric synovial sarcoma highlighting that epigenetic compounds could be used also in pediatric sarcomas." (PMID 28380437, 2017). "In summary evidence suggests that imbalance of SWI/SNF-PRC2/EZH2 can drive oncogenesis in sarcomas." (PMID 27125524, 2016). "The scatter plots of EZH2 expression and these immune infiltration cells in GBM, LUSC, TGCT, and sarcoma (SARC) further confirmed that EZH2 might suppress antitumor immunity by reducing the antitumor immune cell infiltration, leading to unfavorable prognosis in patients with various cancers." (PMID 36545914, 2023). "In addition, EZH2 was shown to govern bone development and sarcoma pathogenesis." (PMID 36622753, 2023). "Thus, EZH2 represents a potential therapeutic target in a range of sarcomas, and clinical studies should therefore investigate the effect of tazemetostat in other sarcoma subtypes." (PMID 34188019, 2021). "Indeed, EZH2 inhibitor has been recently approved by the FDA for this sarcoma." (PMID 34299136, 2021). "Likewise, EZH2-targeted therapy against CSCs could be proposed, since its overexpression has been detected in several tumors, including sarcomas." (PMID 32532153, 2020). "Additionally, EZH2 mRNA in cell lines of other sarcomas was also investigated." (PMID 30120321, 2018). "Could this strategy be relevant to other sarcomas with INI1/EZH2 alteration?" (PMID 27125524, 2016). "The EZH2 pathway is upregulated and there is an increase in H3K27-me3 across CSCs from different sarcoma subtypes." (PMID 39789291, 2025). "Two patients each with refractory, metastatic, sarcoma NOS harboring a SMARCB1 deletion and BRAFV600E had a durable partial response to tazemetostat, an EZH2 inhibitor and a rapid response to vemurafenib and trametinib, respectively." (PMID 35705558, 2022). "Recently, the new and first-in-human EZH2 inhibitor, tazemetostat, showed an encouraging anti-tumor activity in SMARCB1-deleted sarcomas." (PMID 32532153, 2020). "Our findings are in agreement with the observation that EZH2 and the DNA methyltransferase DNMT1 interact with each other and co‐operate in silencing genes in U2OS sarcoma cells." (PMID 31468686, 2019). "In order to know the difference in expression level of EZH2 mRNA between LMS and other sarcomas, we investigated EZH2 mRNA in 8 kinds of sarcoma tissues." (PMID 30120321, 2018). "Yet, the role of EZH2 in sarcoma CSC pathophysiology is not known and warrants further investigation." (PMID 39789291, 2025). "Interestingly, we were unable to generate viable EZH2-knockout cell lines using CRISPR, suggesting the importance of this pathway in sarcoma." (PMID 39789291, 2025). "For example, interleukin signaling was enriched in genes from RBNSig of LIHC and LUAD only, and the enhancer of zeste homolog 2 (EZH2), a histone methyltransferase and catalytic subunit of polycomb repressive complex 2 (PRC2) was specific to RBNSig of LIHC, lung squamous cell carcinoma, and sarcoma." (PMID 40138429, 2025).
breast tumor (46 papers, 2006 to 2025). "The loss of expression of EZH2 in a murine BRCA2-deficient breast tumour model was associated with acquired PARPi resistance through replication fork stabilization." (PMID 39796639, 2024). "In breast tumor samples, the existing association between EZH2 and its target genes correlated the findings from gene expression MERAV database with some variation." (PMID 30760814, 2019). "This raises the question if not only BRCA1-deficient breast tumors but also sporadic basal-like tumors would be dependent on EZH2 overexpression." (PMID 19709408, 2009). "Our group previously showed that EZH2 is functionally relevant in BRCA1-deficient breast tumors and blocking EZH2 enzymatic activity could be a potent treatment strategy." (PMID 35715861, 2022). "Similarly, studies in a number of cancers have found miR-101 to function as a tumor suppressor by targeting EZH2, yet it was also implicated as a promoter of growth in estrogen receptor (ER)-positive breast tumors by inducing the activation of Akt." (PMID 26472042, 2015). "The availability of a small molecule inhibitor such as DZNep allowed us to test whether pharmacological targeting of EZH2 function provides a selective approach to kill BRCA1-deficient breast tumor cells." (PMID 19709408, 2009). "Another possible explanation for the selective overexpression of EZH2 in BRCA1-deficient breast tumors could involve a role of EZH2 in the cell of origin." (PMID 19709408, 2009). "We identified the combined inhibition of EZH2 and the proximal DNA damage response kinase ATM as a novel synthetic lethality-based therapy for the treatment of BRCA1-deficient breast tumors." (PMID 35715861, 2022). "Here we show that in almost all cases, when comparing breast tumors to adjacent normal ducts, PTEN expression is decreased and the PRC2-associated methyltransferase EZH2 is increased." (PMID 33750924, 2021). "Immunohistochemistry in primary breast tumor tissue array showed tumor dependent expression of EZH2." (PMID 30760814, 2019). "In MERAV expression database, there existed a significant difference in the expression of EZH2 in grade 1, grade 2 and grade 3 breast tumor when compared to normal breast tissue (Fig. 1Aiii)." (PMID 30760814, 2019). "Relative expression observed in online MERAV expression dataset showed an enhanced EZH2 expression in primary breast tumors of increasing grade." (PMID 29940916, 2018). "Immunohistochemistry in primary breast tumors of different grades showed a correlated expression of estrogen-related receptors and EZH2." (PMID 29940916, 2018). "Further, EZH2 activates RAF1-β-catenin signaling pathway that promotes expansion of breast tumor initiating cells." (PMID 28410242, 2017). "Here, we described ZLD1039 a potent, highly selective, and orally bioavailable small molecule inhibitor of EZH2, which inhibited breast tumor growth and metastasis." (PMID 26868841, 2016). "In breast tumor initiating cells, increased EZH2 expands cell population through repressing RAD51 expression, and knockdown of EZH2 reduces the repression of RAD51 transcription by decreasing H3K27 trimethylation." (PMID 27494834, 2016). "To examine the pathological relevance of EZH2 regulation by GSK3β, we analyzed correlation between the activity of GSK3β and the enzymatic activity of EZH2 in human breast tumor specimens." (PMID 27494834, 2016). "Stefansson demonstrated that the EZH2-mediated epigenetic repression of DNA damage repair in breast tumors promoted the expansion of breast tumor-initiating cells, potentially contributing to cancer progression." (PMID 26452129, 2015). "SiRNA knockdown in the MDA-MB-231 breast tumour cell line was used to examine the effect of combined inhibition of EZH2 and EHMT2 expression on epigenetic regulation at select target genes, compared to knockdown of either gene alone." (PMID 26300989, 2015).